GAA (alpha glucosidase)
Diseases named in the same sentence as GAA in open-access papers (continued):
Sharing a sentence is not in itself a finding about the gene and the disease.
Krabbe disease (3 papers, 2022 to 2023). A lysosomal disorder that affects the white matter of the central and peripheral nervous systems. "Blind-3 was included in this study, although it was a PT specimen for Krabbe disease that had been designed to demonstrate deficient activity for galactocerebrosidase (GALC) but normal activities for other enzymes (i.e., GAA and IDUA)." (PMID 36975849, 2023).
respiratory failure (3 papers, 2021 to 2024). The significant impairment of gas exchange within the lungs resulting in hypoxia, hypercarbia, or both, to the extent that organ tissue perfusion is severely compromised. "The phrenic-diaphragm motor system is affected preferentially, and respiratory failure often occurs despite GAA enzyme replacement therapy." (PMID 37583873, 2023).
Alzheimer disease (2 papers, 2023 to 2024). A progressive, neurodegenerative disease characterized by loss of function and death of nerve cells in several areas of the brain leading to loss of cognitive function such as memory and language. "Suppression of a strong ISS motif with the intent to induce exon re-inclusion has been previously investigated as a therapeutic strategy in ApoER2, GAA and SMN2 genes, which underlie Alzheimer disease, Pompe disease and spinal muscular atrophy, respectively." (PMID 38182646, 2024).
Chronic Heart Failure (2 papers, 2022 to 2023). "The Prospective Comparison of Luseogliflozin and Alpha-glucosidase on the Management of Diabetic Patients with Chronic Heart Failure and Preserved Ejection Fraction (MUSCAT-HF) trial was excluded because it focused on echocardiographic outcome and had no outcome of interest." (PMID 36824458, 2023).
Duchenne muscular dystrophy (2 papers, 2018 to 2019). Duchenne muscular dystrophy (DMD) is a neuromuscular disease characterized by rapidly progressive muscle weakness and wasting due to degeneration of skeletal, smooth and cardiac muscle. "Selective type II fiber degeneration has been previously reported in other myopathies such as Duchenne muscular dystrophy, facioscapulohumeral muscular dystrophy, myotonic dystrophy type 226 as well as in the alpha-glucosidase knock-out mouse model that mimics the late-onset form of Pompe disease." (PMID 30914683, 2019).
Hearing impairment (2 papers, 2022 to 2024). A decreased magnitude of the sensory perception of sound. "From animal models, storage of glycogen in the organ of Corti has been assumed as the main cause for hearing impairment associated with GAA gene defects." (PMID 35573665, 2022).
hyperlipidemia (2 papers, 2023). "Anti-diabetic drugs including metformin, alpha-glucosidase inhibitors, pioglitazone, dipeptidyl-peptidase-4 inhibitors and glucagon-like peptide 1 analogues have been shown to ameliorate postprandial hyperlipidemia." (PMID 37762244, 2023).
insulin-dependent diabetes (2 papers, 2012 to 2022). "Alpha-glucosidase and α-amylase inhibition could the mechanisms through which the 50% ethanolic extract of O. stamineus and sinensetin exert their antidiabetic activity, indicating that it could have potential use in the management of non-insulin-dependent diabetes." (PMID 23039079, 2012).
Late-onset Pompe disease (2 papers, 2019 to 2026). "BACKGROUND: Late-onset Pompe disease (LOPD) is an autosomal-recessive disorder caused by acid α-glucosidase (GAA) deficiency, typically presenting after the first year of life and resulting in systemic glycogen accumulation." (PMID 41668201, 2026). "Late-onset Pompe disease (LOPD) is a rare metabolic disease caused by a deficiency of acid α-glucosidase (GAA) resulting in the accumulation of glycogen in primarily skeletal and cardiac muscles." (PMID 31187190, 2019).
Pancreatic diseases (2 papers, 2022 to 2025). "GLPA (HR: 2.67; 95% CI, 1.00-7.12; P = .050) and alpha-glucosidase inhibitor (HR: 1.76; 95% CI, 1.16-2.65; P = .008) were associated with PaC both in univariable and multivariable analyses adjusting for DM duration, mean HbA1c, and pancreatic diseases." (PMID 36267596, 2022).
Parkinson disease (2 papers, 2010 to 2025). A progressive degenerative disorder of the central nervous system characterized by loss of dopamine producing neurons in the substantia nigra and the presence of Lewy bodies in the substantia nigra and locus coeruleus. "Both meglitinides and alpha-glucosidase inhibitors currently lack direct evidence linking them to the modulation of ferroptosis in the context of Parkinson’s disease." (PMID 40003982, 2025). "GAA did not exhibit neurological signs of parkinsonism (described in around a third of GRN mutation cases) or motor neurone disease (a rare feature)." (PMID 19766663, 2010).
Respiratory insufficiency (2 papers, 2020 to 2022). "Late-onset Pompe disease (LOPD) is a rare, progressive disorder characterized by limb–girdle muscle weakness and/or respiratory insufficiency, caused by acid alpha-glucosidase (GAA) gene mutations and treated with enzyme replacement therapy." (PMID 35159144, 2022). "This deficiency in GAA results in muscle and neuronal glycogen accumulation, which causes respiratory insufficiency." (PMID 32214050, 2020).
sarcopenia (2 papers, 2020 to 2024). Progressive decline in muscle mass due to aging which results in decreased functional capacity of muscles. "Our study also showed that other hypoglycemic drugs (sulfonylureas/glinides, alpha-glucosidase inhibitors, and insulin) might exert a protective effect on sarcopenia." (PMID 33083494, 2020).
acne (1 paper, 2025). An inflammatory process of the sebaceous glands which is characterized by comedones, nodules, papules and/or pustules on the skin. "Acarbose, an alpha-glucosidase inhibitor, has also been investigated for its role in managing acne in hyperinsulinemic women with PCOS." (PMID 40337376, 2025).
aortic aneurysm (1 paper, 2017). A ruptured aneurysm located in the wall of the proximal portion of the descending aorta proceeding from the arch of the aorta. "Interestingly, there were pleiotropic effects on cardiovascular protection using several OHAs, and their use was also associated with a lower risk of aortic aneurysm growth in Metformin-, sulfonylurea-, and TZD-treated patients but not in patients treated with DPP-4i or alpha-glucosidase inhibitors." (PMID 28697774, 2017).
autism (1 paper, 2013). Persistent deficits in social interaction and communication and interaction as well as a markedly restricted repertoire of activity and interest as well as repetitive patterns of behavior. "Thus, it is possible that deregulation of GAA, KIF1B and SNCA is involved in pathology of human PAX6 patients with a range of neurological disorders including autism, cognitive disorders, epilepsy and mental retardation." (PMID 23342162, 2013).
Autoimmunity (1 paper, 2023). The occurrence of an immune reaction against the organism's own cells or tissues. "Examples of future antigen epitopes or peptides for the treatment of autoimmunity include gliadin (celiac disease), type II collagen (collagen-induced arthritis), alpha-glucosidase (Pompe disease), and Factor VIII (hemophilia A)." (PMID 38202522, 2023).
Azoospermia (1 paper, 2016). Absence of any measurable level of sperm,whereby spermatozoa cannot be observed even after centrifugation of the semen pellet. "It has been reported that seminal plasma alpha-glucosidase activity reflects the functional state of the epididymis and has an important role in azoospermia." (PMID 26884231, 2016).
breast tumor (1 paper, 2019). "This is the first report on these compounds in relation to breast tumor metabolism; the maltose-degrading enzyme (GAA, LYAG) in the MetaCancer study was found down-regulated while the corresponding gene was found significantly down-regulated, consistent with other studies in the GEO meta-analysis." (PMID 31231467, 2019).
cerebral infarction (1 paper, 2020). An ischemic condition of the brain, producing a persistent focal neurological deficit in the area of distribution of the cerebral arteries. "In addition to GAA gene, we examined variations of two panels of genes to explore the mechanism behind the cerebral infarction of the patients." (PMID 32126021, 2020).
cervical cancer (1 paper, 2025). A primary or metastatic malignant neoplasm involving the cervix. "In this study, the HeLa cervical cancer cell model combined with a cervical cancer-bearing mouse model was used to investigate the effect of GaA derivative (GaAD19) on the function of cervical cancer cells." (PMID 41399789, 2025).
colitis (1 paper, 2025). Inflammation of the colon. "Most signals overlapped with the “suspect/interacting” analysis, except for vonoprazan with colitis (ROR = 10.21 [95% CI = 1.93–54.07]) and multiple drugs (several proton pump inhibitors, alpha glucosidase inhibitors, benzodiazepines) with pneumonitis." (PMID 40521636, 2025).
colorectal cancer (1 paper, 2025). A primary or metastatic malignant neoplasm that affects the colon or rectum. "This study investigates MGAM as a potential direct target of alpha‐glucosidase inhibitors in colorectal cancer (CRC), explores its biomarker potential, and evaluates gene expression patterns across diverse cancers." (PMID 40881483, 2025).
deficiencies (1 paper, 2020). "Pompe disease (PD, OMIM #232300), also known as glycogen storage disease type 2 or acid maltase deficiencies, is caused by mutations of the gene coding for the lysosomal α-glucosidase (GAA, E.C.3.2.1.20)." (PMID 32660097, 2020).
dementia (1 paper, 2023). Loss of intellectual abilities interfering with an individual's social and occupational functions. "Approximately 196 out of 100,000 persons developed dementia in the alpha-glucosidase inhibitor group, while ~78 out of 100,000 developed it in the TZD group." (PMID 38152822, 2023).
demyelination (1 paper, 2022). "In animal model of GAA deficient mice both a reduction of sensory dorsal root ganglion cells with axonal damage of sensory neurons as well as glycogen deposits in Schwann cells with signs of nerve demyelination have been reported." (PMID 35477515, 2022).
dental caries (1 paper, 2014). The decay of a tooth, in which it becomes softened, discolored, and/or porous. "Alpha-glucosidase is hypothesized to participate in the induction of dental caries." (PMID 24533043, 2014).
dumping syndrome (1 paper, 2021). A disorder of the gastrointestinal tract. "Treatment with exercise combined with a sodium-glucose co-transporter 2 inhibitor and an alpha glucosidase inhibitor alleviated her glucose intolerance and dumping syndrome-like symptoms, without increasing hypoglycemic events." (PMID 33588940, 2021).
gastric cancer (1 paper, 2020). A primary or metastatic malignant neoplasm involving the stomach. "Like us, other researchers have assessed the effect of different antihyperglycemic medications (insulin, metformin, sulfonylureas, thiazolidinediones, alpha-glucosidase inhibitors, non-sulfonylurea insulin secretory analogues) on gastric cancer risk." (PMID 32033451, 2020).
gastric ulceration (1 paper, 2008). "It inhibits gastric ulceration, protects from gamma radiation, reduces the damage to brain tissue of diabetics and also inhibits alpha-glucosidase activity." (PMID 22275971, 2008).
gingivitis (1 paper, 2015). A disorder involving inflammation of the gums; may affect surrounding and supporting structures of the teeth. "It is also interesting to note that the present study established a correlation between gingivitis and the local Candida enzyme oral activity, including valine arylamidase (E7), alpha-glucosidase (E16), and N-acetyl-beta-glucosaminidase (E18)." (PMID 25952029, 2015).
lactic acidosis (1 paper, 2023). Metabolic acidosis characterized by the accumulation of lactate in the body. "Other side effects include fatigue and lactic acidosis (biguanides), flatulence and diarrhea (alpha-glucosidase inhibitor), and an elevated LDL-cholesterol level (thiazolidinediones)." (PMID 37111281, 2023).
Lafora body disease (1 paper, 2023). "One patient (0.3%) was treated with long-term enzyme replacement therapy for Pompe disease (alpha-glucosidase) and another one (0.3%) received brivaracetam and metformin for Lafora body disease, a type of rare, inherited and severe progressive myoclonic epilepsy." (PMID 36837468, 2023).
mucopolysaccharidosis type I (1 paper, 2020). The most common type of mucopolysaccharidosis. "Indeed, Pompe disease (due to a deficiency of acid alpha-1,4-glucosidase, GAA) and mucopolysaccharidosis type I (MPS I, due to a deficiency of alpha-L-iduronidase, IDUA) have already been added to the US Secretary of Health and Human Services’ Recommended Uniform Screening Panel (RUSP)." (PMID 32802993, 2020).
nonalcoholic fatty liver disease (1 paper, 2023). "Cuminaldehyde was reported to have an inhibitory effect in vitro against rat lens aldose reductase and alpha-glucosidase (human metabolome database) and to protect against nonalcoholic fatty liver disease in rats fed a high-fat diet." (PMID 36624413, 2023).
Onset (1 paper, 2020). The age group in which disease manifestations appear. "Patients with severe infantile-onset Pompe disease can be differentiated into two groups: one group with detectable GAA protein (Cross Reactive Immunologic Material Positive, CRIM+) and another group without any detectable GAA protein (Cross Reactive Immunologic Material Negative, CRIM−)." (PMID 33554498, 2020).
pancreatic cancer (1 paper, 2026).
pulmonary hypertension (1 paper, 2014). Increased pressure within the pulmonary circulation due to lung or heart disorder. "Many genes are functionally related to high-altitude physiology, such as angiogenesis (RGCC), pulmonary hypertension remodeling (PLA2G12A), oxygen intake (C9ORF3), neural response (GRID1 and GRIN2B), melanin synthesis (MITF, PDGFRB and PIK3R3) and heart development (FOXS1, GAA and MYLK2)." (PMID 25270331, 2014).
varicocele (1 paper, 2020). A condition characterized by the dilated tortuous veins of the spermatic cord with a marked left-sided predominance. "The neutral alpha-glucosidase levels in cryptorchid men were also significantly lower than those obtained for men with varicocele and for drivers (p < 0.01 for the varicocele group, p < 0.05 for the drivers group)." (PMID 32899311, 2020).
viral infection (1 paper, 2025). "During his hospitalization he underwent autoimmune and viral infection screening, spirometry, dry blood spot (DBS) for alpha-glucosidase and alpha-galactosidase analyses, and an electrophysiological study, which all revealed normal results." (PMID 41462609, 2025).
metabolic disorder (21 papers, 2021 to 2025). "Pompe disease (PD), also known as glycogenosis type II, is a rare inherited metabolic disorder caused by a deficiency of the enzyme acid alpha-glucosidase (GAA enzyme)." (PMID 39859472, 2025). "In agreement with this pathogenic framework, Pompe disease is a metabolic disorder caused by mutations in the GAA gene on chromosome 17q25.2–q25.3, leading to deficiency of acid α-glucosidase (GAA) and impaired lysosomal glycogen degradation." (PMID 41614773, 2025). "Enzyme replacement therapy (ERT) is the only approved disease-modifying treatment modality for Pompe disease, a rare, inherited metabolic disorder caused by a deficiency in the acid α-glucosidase (GAA) enzyme that catabolizes lysosomal glycogen." (PMID 39494167, 2024). "Pompe disease is a rare, inherited metabolic disorder caused by biallelic pathogenic variants in the acid α-glucosidase (GAA) gene, which encodes a lysosomal enzyme that hydrolyzes glycogen." (PMID 39494167, 2024). "Pompe disease (PD), or glycogen storage disease type II, is an autosomal recessive inherited metabolic disease caused by mutations in acid alpha-glucosidase (GAA; EC 3.2.1.20), a lysosomal enzyme involved in lysosomal glycogen catabolism." (PMID 37569856, 2023). "Pompe disease (PD), also known as acid maltase deficiency or glycogen storage disease type II (GSDII) (OMIM# 232300), is a rare autosomal metabolic disorder caused by a functional deficiency of the acid-alpha glucosidase (GAA) protein." (PMID 35682977, 2022). "Pompe disease is a rare autosomal recessive metabolic disorder caused by mutations in the enzyme coding for acid alpha-glucosidase (GAA) protein." (PMID 35203513, 2022). "Pompe disease, another HCM phenocopy, is a metabolic disease linked to mutations in the GAA gene, with a deficiency of the GAA enzyme involved in the lysosomal glycogen degradation." (PMID 34574061, 2021). "Pompe disease (PD) is an autosomal recessive metabolic disorder caused by pathogenic variants in the acid alpha-glucosidase gene (GAA) that produces biochemical defects in the lysosomal acid alpha 1,4-glucosidase." (PMID 34020684, 2021). "Pompe disease (PD) is an autosomal recessive metabolic disorder caused by pathogenic variants in the acid -glucosidase gene (GAA) that produces defects in the lysosomal acid -1,4-glucosidase." (PMID 34020684, 2021). "Glycogen storage disease type II (Pompe disease) is an autosomal recessive metabolic disorder which damages muscle and nerve cells and results from the accumulation of glycogen in the lysosome due to the deficiency of the alpha-glucosidase enzyme." (PMID 34691145, 2021). "Pompe disease is an inherited metabolic disorder due to the deficiency of the lysosomal acid α-glucosidase (GAA)." (PMID 34565280, 2021). "Pompe disease (also known as glycogen storage disease type II or acid maltase deficiency) is a multisystemic metabolic disease caused by pathogenic variants in the GAA gene that encodes α-alpha-glucosidase (GAA), the enzyme that breaks down glycogen into glucose in lysosomes." (PMID 40329343, 2025). "Pompe disease (PD) is a rare inherited metabolic disorder of deficient or absent acid alpha-glucosidase (GAA), resulting in defective lysosomal glycogen catabolism." (PMID 37841659, 2023).
cancer (11 papers, 2011 to 2025). A tumor composed of atypical neoplastic, often pleomorphic cells that invade other tissues. "Alpha glucosidase inhibitor use was associated with increased risk of cancer (13 studies, RR = 1.10, 95% CI 1.05-1.15)." (PMID 26076034, 2015). "On the other hand, insulin, sulfonylureas and alpha glucosidase inhibitor use was associated with an increased risk of cancer incidence (RR = 1.21, 95% CI 1.08-1.36, I2 = 96.31%; RR = 1.20, 95% CI 1.13-1.27, I2 = 95.02%; RR = 1.10, 95% CI 1.05-1.15, I2 = 0.00% respectively)." (PMID 26076034, 2015). "This comprehensive approach will provide valuable insights into the therapeutic potential of alpha‐glucosidase inhibitors for cancer treatment." (PMID 40881483, 2025). "The treatments analyzed (within 3 years prior to cancer diagnosis) were: insulin glargine, insulin detemir, human insulin, fast-acting insulin and analogues, metformin, sulfonylureas, repaglinide, thiazolidinediones, dipeptidyl peptidase-4 inhibitors, and alpha glucosidase inhibitors." (PMID 24278227, 2013). "Considering that alpha-glucosidase and PTP1B also play an important role in cancer, it seems useful to investigate if the alpha-glucosidase and PTP1B inhibition of BPs is relevant for their anticancer activity." (PMID 21822416, 2011).